MMP25-AS1 (MMP25 antisense RNA 1)
Gene: Long non-coding RNA gene on chromosome 16 (3,037,233 to 3,059,370, reverse strand). Ensembl gene ENSG00000261971.
Diseases named in the same sentence as MMP25-AS1 in open-access papers:
MMP25-AS1 is named in the same sentence as 1 disease in open-access papers, as found by Europe PMC text mining. Sharing a sentence is not in itself a finding about the gene and the disease.
MMP25-AS1 shares sentences with these, for which no sentence is quoted: myocardial infarction (1 paper).